PFKFB3 (6-phosphofructo-2-kinase/fructose-2,6-biphosphatase 3)
Diseases named in the same sentence as PFKFB3 in open-access papers (continued):
Sharing a sentence is not in itself a finding about the gene and the disease.
tumor (268 papers, 2005 to 2026). "These clinical findings directly linked elevated PFKFB3 expression to both tumour progression and a high‐stiffness microenvironment, in agreement with the findings in vivo and in vitro." (PMID 41292194, 2025). "Clinically, elevated PFKFB3 expression is associated with advanced tumor stages, tumor size, and lymph node metastasis, suggesting its potential as a prognostic biomarker." (PMID 41220952, 2025). "In conclusion, we observed a positive association between nuclear PFKFB3 protein levels and tumor grade." (PMID 40022029, 2025). "Soluble factor hyaluronic acid, derived from tumors, induce upregulation of PFKFB3 in tumor-associated monocytes, which promotes PD-L1 expression by activating NF-κB signaling." (PMID 39897050, 2025). "In order to evaluate the effects of PFKFB3 loss on tumor initiation and early tumor development, we crossed Cre/Pfkfb3fl/fl mice with K-rasLA1 mice and treated K-rasLA1/Cre/Pfkfb3fl/fl mice with vehicle ± TAM at 6 weeks of age for 5 days." (PMID 39001392, 2024). "Mechanistically, Aurora-A acts as a protein phosphorylation kinase that directly interact with and phosphorylate PFKFB3 at S461, in turn promoting the glycolysis process of tumor cells and causing metabolic reprogramming of tumor cells." (PMID 36990998, 2023). "PFKFB3, as a key regulator of glycolysis, has been implicated in tumorigenesis, angiogenesis chemoresistance, and tumor microenvironment." (PMID 37293295, 2023). "The mRNA and protein levels of PFKFB3 increased in different tumors, and PFKFB3 overexpression was observed to be associated with lymphatic metastasis, tumor staging, and poor prognosis." (PMID 37476196, 2023). "The results of clinicopathologic correlation analysis indicated that PFKFB3 overexpression was significantly associated with higher blood glucose level (P = 0.018), larger tumor size (P = 0.006) and worse TNM stage (P = 0.027)." (PMID 35094634, 2022). "The PFKFB3 isoform is ubiquitously expressed and has been implicated in glucose metabolism during neoplastic disease but also plays a critical role in endothelial cells, coordinating angiogenic sprouting during physiologic states or malignancy." (PMID 36326834, 2022). "Taken together, our findings prove specific, dose-dependent effects of PFKFB3 splice variants on the growth capacity of tumor cells and HEK-293 cells." (PMID 34234350, 2021). "A high rate of glycolysis is considered a hallmark of tumor progression and is caused by overexpression of the enzyme 6-phosphofructo-2-kinase/fructose-2,6-biphosphatase 3 (PFKFB3)." (PMID 33922320, 2021). "PFKFB3 expression has been directly associated with enhanced glycolysis, not only in cancer cells but also within the tumor environment." (PMID 33671096, 2021). "In tumor vasculature, PFKFB3 has been implicated in vessel destabilization due to VE-cadherin internalization." (PMID 34084561, 2021). "PFKFB3, a key glycolytic enzyme, is upregulated in tumor-associated monocytes, and leads to the activation of glycolysis, and this can induce PD-L1 expression, and subsequently attenuate the response of cytotoxic T lymphocyte in tumor tissues." (PMID 34638609, 2021). "Based on the correlation and expression analyses, PFKFB3 expression was associated with tumor progression in all breast subtypes." (PMID 31428701, 2019). "In the study of PFKFB3 expression and clinical features of patients, we found that PFKFB3 expression was associated with tumor size and patient survival and played an important role in tumor growth." (PMID 29559632, 2018). "We report that PFKFB3 was mainly located in the nucleus in tumor cells and that PFKFB3 overexpression was associated with tumor progression by directly regulating cell proliferation." (PMID 29559632, 2018). "The results showed that higher expression of PFKFB3 was associated with larger tumor size (p = 0.04), poorer OS (p = 0.027), and disease-free survival (DFS) (p = 0.004)." (PMID 29559632, 2018).
tumor (continued). "PFKFB3 overexpression was associated with large tumor size (p = 0.04) and poor survival of patients with HCC (p = 0.027)." (PMID 29559632, 2018). "As a vital regulator of glycolysis, accumulating studies have suggested that PFKFB3 is associated with many aspects of cancer, including carcinogenesis, cancer cell proliferation, vessel aggressiveness, drug resistance and tumor microenvironment." (PMID 29263928, 2017). "There is also a marked switch from expression of the liver isoform of 2,6-phosphofructo-2-kinase/fructose-2,6-biphosphatase (encoded by PFKFB1) to the PFKFB3 isoform, the type of which is also commonly found in tumor cells." (PMID 29109698, 2017). "This can explain why even the deletion of one allele of PFKFB3 or the use of a low dose of 3PO already induces tumor vessel normalization." (PMID 28081641, 2017). "Consistently, treatment with a high dose of the PFKFB3 blocker 3-(3-pyridinyl)-1-(4-pyridinyl)-2-propen-1-one (3PO) suppresses tumor EC proliferation and promotes EC death, ultimately causing tumor vessel disintegration." (PMID 29321777, 2017). "The activity and localization of these splicing variants may contribute to the regulation and function of PFKFB3 in glycolysis of tumor cells, as well as its requirement for tumor growth." (PMID 39318551, 2024). "We therefore speculated that reduced tumor growth caused by Pfkfb3 deletion might be due in part to an increase in apoptosis." (PMID 39001392, 2024). "Therefore, it can be proposed that low-level autophagy causes PFKFB3 stabilization to cause a switch from dormant tumor to active metastatic tumor cells." (PMID 36831154, 2023). "PFKFB3 was also associated with tumor stage, grade and serous subtype." (PMID 35155224, 2022). "PFKFB3 overexpression has been associated with a poor prognosis in various neoplastic diseases." (PMID 34831136, 2021). "In addition, vascular endothelial growth factor (VEGF) signalling by tumours causes 6-phosphofructo-2-kinase/fructose-2,6-biphosphatase 3 (PFKFB3) upregulation in ECs, which activates PFK-1 to further augment the glycolytic phenotype." (PMID 33092283, 2020). "PFKFB3 overexpression has been associated with a large tumor size and poor survival in patients, while PFKFB3 knockdown inhibits HCC growth by reducing glucose consumption and impeding DNA repair, which leads to cell cycle arrest at the G2/M phase and apoptosis." (PMID 30234009, 2018). "In animal studies, overexpression of PFKFB3 is associated with increased tumor growth." (PMID 29559632, 2018). "It will remain to be determined whether a high, or rather a low, dose of the PFKFB3 blocker is capable of inducing tumor vessel normalization, and its associated therapeutic benefits of reduced metastasis and improved response to chemotherapy." (PMID 28081641, 2017). "Additionally, PFKFB3 activation has been linked to the impairment of endothelial barrier function within the tumor microenvironment by promoting VE-cadherin endocytosis in endothelial cells and reducing the adhesive properties of pericytes through downregulating N-cadherin expression." (PMID 38033124, 2023). "In HCC, PFKFB3 activates the protein kinase B (Akt)/excision repair cross complementation group 1 pathway, enhancing DNA repair and tumor growth." (PMID 40818043, 2026). "This coordinated reprogramming suggests that PFKFB3 serves as a metabolic integrator coordinated multiple metabolic pathways to support tumor-promoting functions of TAMs." (PMID 41516095, 2025). "The immunohistochemical staining represents nuclear PFKFB3 protein, while the RNA levels are based on material from a whole tumor tissue punch." (PMID 40022029, 2025). "In breast cancer, tRiMetF31 has been mechanistically demonstrated to suppress tumor angiogenesis and metastatic dissemination through direct targeting of PFKFB3." (PMID 40265011, 2025). "Relationship between PFKFB3 expression and clinicopathological features in tumour tissues of HCC patients." (PMID 41292194, 2025).
tumor (continued). "This process results in HIF-1α transcriptional upregulation of PD-L1 expression, further promoting tumor immune evasion, which mitigates the cytotoxic effect of selective PFKFB3 inhibitors." (PMID 39897050, 2025). "For example, Inhibiting the glycolytic activator PFKFB3 in tumor pericytes can normalize tumor vasculature and improve drug delivery." (PMID 40784879, 2025). "Among the four subtypes of PFKFB, PFKFB3 possess a distinctly higher kinase/phosphatase activity ratio, rendering it a crucial enzyme in regulating the glycolytic flux of tumor cells." (PMID 39897050, 2025). "Glucose metabolism is an important energy source process to support tumor cell metabolism, in which glycolysis plays a central role, and PFKFB3 is one of the key enzymes involved in glycolytic metabolism." (PMID 40014905, 2025). "As indicated by the immunohistochemistry (IHC) results, ATF4 or PFKFB3 knockdown decreased the staining intensity of Ki67, a proliferation marker of tumor cells." (PMID 40919132, 2025). "PFKFB3 overexpression or silencing inhibited or promoted tumor cell proliferation, respectively, following cell treatment with 5-FU." (PMID 40014905, 2025). "The estrogen response pathways were highly enriched with increasing PFKFB3 protein groups, consistent with PFKFB3 being enriched in hormone positive tumor subtypes." (PMID 40022029, 2025). "Accumulating evidence for the role of the glycolytic activator PFKFB3 in angiogenesis and vessel barrier function further supports the notion of metabolism acting as a driving force in tumor blood vessel dysfunction." (PMID 39567756, 2025). "Among these, the PFKFB3 inhibitor PFK158 has shown significant effects in anti-tumor and anti-angiogenesis applications and has entered Phase I clinical trials (ClinicalTrials.gov: NCT02044861)." (PMID 41471391, 2025). "Blocking its activity using PF-543, an inhibitor of SPHK1, attenuated angiogenesis and tumor growth in an HCC model by triggering proteasomal degradation of PFKFB3." (PMID 39567756, 2025). "It has been demonstrated that inhibition of PFKFB3 reduces glycolysis in ECs in the TME to prevent the proliferation of tumor cells." (PMID 40045411, 2025). "ATF4 or PFKFB3 knockdown significantly suppressed the xenograft tumor growth, as measured by the end point tumor weight." (PMID 40919132, 2025). "Meanwhile, PFKFB3 in HCC tissues in normal liver stiffness group mainly distributed in the cytoplasm of tumour cells, but in high liver stiffness group, PFKFB3 expression occurred in both the cytoplasm and the nucleus." (PMID 41292194, 2025). "The results revealed that high PFKFB3 expression was positively correlated with larger tumour size, as well as increased expression of COL1, LOX and the COL1High/LOXHigh signature." (PMID 41292194, 2025). "Inhibition of endothelial glycolysis through PFKFB3 blockade has been shown to reduce pathological angiogenesis in several disease models, including tumor neovascularization." (PMID 41235226, 2025). "Second, PFKFB3 is highly expressed in endothelial cells and promotes tumor angiogenesis by activating the HIF-1α/VEGF pathway." (PMID 40438141, 2025). "High number of PFKFB3+ cells was observed in tumor tissues, and these cells were single infiltrating cells." (PMID 41516095, 2025). "Overall, PFKFB3, an indirect rate‐limiting enzyme for glycolysis, mediates matrix stiffness‐promoted tumour growth and proliferation." (PMID 41292194, 2025). "Both pharmacological inhibition and partial deletion of endothelial PFKFB3 reduced tumor vascularization and metastasis, while also increasing vessel stability, which aided drug delivery and enhanced the effect of chemotherapy in a murine liver cancer model." (PMID 41235226, 2025). "Overexpression of PFKFB3 not only drives glycolysis but also modifies immune cell behavior within the tumor microenvironment." (PMID 41220952, 2025). "More importantly, using PFK15 or shPFKFB3 to inhibit PFKFB3 can significantly reduce tumor growth in vivo." (PMID 41000074, 2025).
tumor (continued). "PFKFB3 primarily catalyzes the synthesis of fructose-2,6-bisphosphate (F2,6BP), enhancing glycolytic flux and promoting the rapid proliferation of tumor cells." (PMID 40438141, 2025). "In our study we demonstrate that PFKFB3 is predominantly expressed in TAMs in CRC tumor microenvironment." (PMID 41516095, 2025). "This was also observed in DEN-treated mice, where elevated PFKFB3 levels in tumor endothelial cells and adjacent tumorous tissues were dramatically attenuated by PF-543 administration." (PMID 38200582, 2024). "As an indirect stimulator of glycolysis, PFKFB3 influences the glycolytic activity of cancer and tumor endothelial cells (TEC) and is therefore involved in rapid vasculature growth and subsequent tumor vessel abnormalities." (PMID 39007350, 2024). "Studies have reported that PFKFB3 mediates circadian rhythm control of tumor growth, underscoring the significance of time-based PFKFB3 inhibition in cancer treatment." (PMID 38903177, 2024). "Mechanistically, PF-543 treatment reduced S1P production in endothelial cells, which impaired the PFKFB3-mediated glycolytic energy supply for tumor angiogenesis." (PMID 38200582, 2024). "Similar to the Erbb2 model, to control for unanticipated effects of TAM on tumor growth, we also examined tumor growth in K-rasLA1/Cre/Pfkfb3+/+ mice (WT for Pfkfb3) administered vehicle ± TAM and found similar growth in both groups." (PMID 39001392, 2024). "Of these functions, the role of PFKFB3 in tumor glucose metabolism has been extensively interrogated." (PMID 39001392, 2024). "Taken together, these results reveal that 3PO administration lowers PFKFB3 expression in tumor tissue, thereby enhancing RT effects, increasing cell death and reducing RC proliferation in vivo." (PMID 39007350, 2024). "Tumor-derived hyaluronic acid fragments can also upregulate PFKFB3 expression in TAMs, promoting glycolysis and PD-L1 expression." (PMID 38840205, 2024). "Previous data from our laboratory have shown that PFKFB3 inhibition reduced tumor cell viability and xenograft growth in part by inducing apoptosis." (PMID 39001392, 2024). "To evaluate the functional consequences of Pfkfb3 deletion in vivo, we crossed Cre-bearing Pfkfb3fl/fl mice with oncogene-driven tumor models and found that Pfkfb3 deletion markedly decreased their glucose uptake and growth." (PMID 39001392, 2024). "Knockout (KO) or inhibition of PFKFB3 inhibits tumor angiogenesis, growth and metastasis, promotes tumor vessel normalization and improves chemotherapy, irrespective of VEGF-A presence." (PMID 38200582, 2024). "Glut1, Ldha, and Pfkfb3 were overexpressed in moderately to severely enlarged tumors, while Glut3 and Aldoa displayed a significant downregulation in the most advanced tumor stage." (PMID 39684459, 2024). "Targeting PFKFB3-mediated glycolytic energy supply for tumor angiogenesis represents a distinct, potentially superior anti-angiogenic strategy, compared to molecularly targeting individual pro-angiogenic drivers." (PMID 38200582, 2024). "One key study demonstrated that tumour-derived hyaluronan fragments induced the upregulation of a key glycolytic enzyme, PFKFB3, in tumour-infiltrating monocytes/macrophages." (PMID 39684877, 2024). "One subject of intense research so far was the study of the role of the 6-phosphofructose-2-kinase fructiose-2,6-biphosphatase 3 (PFKFB3), that is generally upregulated in tumor endothelial cells." (PMID 38164151, 2024). "Our data establish a new and effective model for examining the regulation of glucose metabolism by PFKFB3 and highlight its importance in tumor growth." (PMID 39001392, 2024). "We also have evaluated the functional effects of Pfkfb3 deletion in relevant oncogene-driven spontaneous models of cancer where we have found that PFKFB3 enzyme activity is required for tumor initiation and growth." (PMID 39001392, 2024).
tumor (continued). "Given the key function of F26BP in tumor glycolysis and growth, the high kinase activity of PFKFB3 and its production of F26BP indicate an important role for this enzyme in tumor proliferation and glucose metabolism." (PMID 39001392, 2024). "Previous studies from our laboratory determined that oncogene-transformed primary cells required PFKFB3 at wild-type levels of expression to support the development and growth of colonies in soft agar and tumor growth in vivo." (PMID 39001392, 2024). "Within the PFKFB4 family, PFKFB3 has emerged as a pivotal figure in tumor glycolysis, carrying substantial implications for both tumor growth and metastasis." (PMID 38538285, 2024). "In tumor microvessels, PFKFB3 inhibition via 3PO reduces the expression of EC adhesion molecules by inhibiting the NF-κB signaling pathway." (PMID 39318551, 2024). "This key finding not only confirms the crucial role of PFKFB3 in tumor metabolism regulation but also opens up new strategies for cancer treatment." (PMID 39877360, 2024). "6-phosphofructo-2-kinase/fructose-2,6-bisphosphatase 3 (PFKFB3) mediated the expression of PD-L1 by activating NF-κB signaling in the tumor microenvironment." (PMID 38155974, 2023). "PFKFB3 inhibitor in endothelial cells can improve vascular maturation and perfusion, restrain tumor invasion, intravasation and metastasis, and thus can be considered as a promising therapeutic target." (PMID 37143105, 2023). "A transient inhibition of PFKFB3 in endothelial cells using 3-(3-pyridinyl)-1-(4-pyridinyl)-2-propen-1-one (3PO) induced tumor vessel normalization, impaired metastasis, and improved chemotherapy." (PMID 36768924, 2023). "Related studies have shown that PFKFB3 is a direct target of miR-206, which inhibits glycolytic metabolism in tumor cells by downregulating PFKFB3 and acts as a tumor inhibitory factor." (PMID 37204526, 2023). "The inhibition of glycolysis of endothelial cells by targeting PFKFB3 can reduce the metastasis of tumor cells by normalizing tumor blood vessels." (PMID 37476196, 2023). "PFKFB3 expression was slightly higher in the tumor tissues than in the tumor-adjacent normal tissues (p = 0.098)." (PMID 37919747, 2023). "The selective inhibition of PFKFB3 displays broad anti-tumor activity in syngenic pre-clinical models and early human studies by inducing necroptotic cell death, apoptosis, cell cycle arrest, and inhibiting invasion." (PMID 36768924, 2023). "Among the 4 isoenzymes, Pfkfb3 exhibits the highest kinase/phosphatase ratio (740:1) and is the most studied isoform in tumor cells." (PMID 38813509, 2023). "More importantly, the suppression of PFKFB3 by PFK15 or shPFKFB3 led to markedly reduced tumor growth in vivo." (PMID 36740704, 2023). "Taken together, our findings corroborated that Aurora-A affects the glycolytic flow of tumor cells through distinct mechanisms, and suggested that Aurora-A promoted glycolysis by increasing the phosphorylation level of the PFKFB3 S461 site in TC cells." (PMID 36990998, 2023). "An increasing body of evidence suggests that inhibition of PFKFB3 by chemical inhibitors or genetic attenuation significantly reduced glycolytic flux, ras-based transformation, and tumor growth in athymic mice." (PMID 36990998, 2023). "As a glycolysis-related enzyme, PFKFB3 is emerging as a potential target for tumor diagnosis and treatment in that it is highly expressed in almost all tumor tissues." (PMID 37035116, 2023). "We elucidated the relationship between hypoxia and PFKFB3, which was upregulated in tumor aerobic glycolysis." (PMID 37476196, 2023). "On the one hand, glycolysis shutdown by blocking the glycolytic activator PFKFB3 leads to tumor vessels normalization and enhanced drug delivery." (PMID 36631598, 2023). "The glycolysis inhibitor 2-DG reserved the cell proliferation, migration and invasion in Aurora-A-overexpressed KTC-1 cells, also suggesting that Aurora-A promoted tumor progression by mediating PFKFB3-mediated glycolysis." (PMID 36990998, 2023).